LEP (leptin)
Diseases named in the same sentence as LEP in open-access papers (continued):
Sharing a sentence is not in itself a finding about the gene and the disease.
Obesity (continued). "Low-grade inflammation due to exaggeration of inflammatory signaling pathways and increasing the release of pro-inflammatory cytokines, mainly IL-1β, IL-6, and TNF-α induce brain leptin resistance in obesity." (PMID 40498212, 2025). "A cross-sectional study in humans suggest that leptin, typically high in individuals with obesity, promotes autoreactive T-cell proliferation and proinflammatory cytokine secretion." (PMID 39885338, 2025). "For example, the fat mass and obesity-associated gene (FTO) and the leptin gene (LEP) influence metabolic diseases and hormonal regulation, contributing to obesity." (PMID 40218949, 2025). "In cardiovascular disease research from high-income countries, individuals with obesity typically have lower adiponectin and higher leptin levels." (PMID 40486661, 2025). "Although elevated leptin levels in obesity are supposed to lower food intake and increase energy expenditure, “leptin resistance” confuses this relationship." (PMID 40002424, 2025). "Other potential mediators of impaired leptin action in obesity include obesity-induced inflammation, cellular endoplasmic reticulum stress, and LepRb deacetylation." (PMID 40393800, 2025). "On the other hand, it has been observed that obesity from hyperalimentation negatively affects the secretion of insulin, leptin, and adiponectin." (PMID 40283681, 2025). "Alterations in gut microbiota composition, often observed in obesity and metabolic syndrome, can exacerbate leptin resistance and inflammatory processes via bacterial translocation and LPS-mediated activation of the JAK-STAT pathway." (PMID 40095902, 2025). "JNK’s role extends beyond peripheral tissues, as hypothalamic JNK activation in diet-induced obesity disrupts leptin signaling, promoting hyperphagia and further adiposity." (PMID 40699756, 2025). "This resistance diminishes leptin's ability to regulate appetite and energy expenditure, representing a major obstacle to the development of effective leptin-based obesity treatments." (PMID 41016636, 2025). "Since people with obesity paradoxically have higher leptin levels, it has been suggested that leptin resistance develops, inhibiting the hormone’s ability to regulate hunger." (PMID 40219007, 2025). "In 1999, Dr. Farooqi’s research team published a seminal paper describing a nine-year-old girl with severe, early-onset obesity and undetectable serum leptin levels, who was treated with recombinant human leptin." (PMID 40415699, 2025). "Combining CCK with other hormones such as GLP-1, amylin, or leptin shows promise for synergistic effects in treating obesity and T2DM, highlighting the therapeutic potential of CCK-based strategies." (PMID 41150735, 2025). "Additional differences included significantly higher leptin (105% higher) and lower adiponectin (84% lower) in individuals with obesity than in lean controls." (PMID 40548377, 2025). "In humans with obesity, LEP UE methylation is associated with body fat percentage, with leptin serum levels potentially acting as a mediator exclusively in females." (PMID 39934931, 2025). "Obesity exacerbates inflammation through immune cell activation in adipose tissue and the release of proinflammatory adipokines, such as leptin, resistin, and IL-18, which enhance autoimmune responses and insulin resistance." (PMID 40277935, 2025). "NW-A had the highest DII score, whereas OO-A showed higher levels of leptin, an inflammatory cytokine, which is elevated in obesity and plays an important role in respiratory diseases, including asthma." (PMID 41256924, 2025). "Inhibition of LepRb intracellular signaling by JAK2 dephosphorylation is a potential contributor to leptin resistance in obesity." (PMID 41251447, 2025). "Further, continued obesity for long-term periods after parturition can exacerbate the problem of high leptin and NEFA levels, which can further impair the actions of insulin, as well as the metabolism of amino acids, lipids, and glucose in mothers." (PMID 41463818, 2025).
Obesity (continued). "Leptin, a product of the obesity gene, plays a key role in energy homeostasis and is known to exert biological functions through the leptin receptor (Ob‐R)." (PMID 40620232, 2025). "According to the literature, in young girls, early-onset obesity accelerates pubertal timing, mediated in part by leptin-driven activation of the HPG axis." (PMID 41226484, 2025). "In individuals with obesity increased leptin secretion lead to leptin resistance, which represent a significant barrier to successful weight loss." (PMID 40607230, 2025). "Human and translational evidence supports leptin’s dual direct and central actions on bone, while indicating context-dependence in obesity and diabetes." (PMID 41002965, 2025). "In contrast to the control group, circulating leptin and resistin levels were increased along with serum proinflammatory cytokines in obesity and diabetes." (PMID 40095937, 2025). "Adipokines such as leptin and insulin play an important role in the regulation of appetite and energy metabolism, and their resistance usually leads to the development of obesity." (PMID 41199858, 2025). "To date, mechanistic understanding of the effects that leptin has on host responses to respiratory viral infections leading to increased viral replication and disease severity in people with obesity and T2DM is not fully understood." (PMID 40125513, 2025). "Further elucidation of the gut-brain axis is expected to become a new option for obesity treatment through leptin resistance." (PMID 39897330, 2025). "In contrast, in obesity or metabolic syndrome, it appears to impair endothelial responses, suggesting the emergence of leptin resistance." (PMID 41470134, 2025). "Obesity-triggering nutrients affect adipocytes, whereas proinflammatory leptin prompts the generation of cytokines and T cells." (PMID 40494849, 2025). "In the context of obesity, impaired secretion of adiponectin and leptin leads to decreased breakdown of fatty acids and heightened fat storage." (PMID 40016558, 2025). "Monogenic obesity, often characterized by early-onset and severe obesity, results from rare mutations in genes such as LEP (leptin), MC4R (melanocortin 4 receptor), and SH2B1 (SH2B adaptor protein 1)." (PMID 40004938, 2025). "Leptin resistance, common in obesity, further blunts central respiratory drive, exacerbating hypoventilation and hypercapnia." (PMID 41523475, 2025). "Women with severe obesity had higher circulating leptin levels than men and these levels strongly correlated with body size measurements for both sexes when BMI was considered as a confounding factor." (PMID 40943431, 2025). "Elevated leptin in obesity promotes Th17 cell polarization, while decreased adiponectin removes an anti-inflammatory control, further fueling psoriatic inflammation." (PMID 39858932, 2025). "Leptin resistance remains a major challenge in obesity treatment, limiting the efficacy of leptin-based therapies." (PMID 41016636, 2025). "Obesity induces a chronic low-grade systemic inflammatory state, wherein adipose tissue dysfunction leads to abnormal secretion of adipokines (e.g., leptin and adiponectin) and pro-inflammatory cytokines such as TNF-α, IL-6, and IL-1β." (PMID 41305576, 2025). "For example, in knee synovial fluid samples of patients with obesity and OA, levels of adiponectin, leptin, resistin, and visfatin were found to be elevated." (PMID 39152660, 2025). "Biologically, once overweight, an individual is more likely to develop obesity because of physiological mechanisms (e.g., leptin resistance, altered neuroendocrine signaling) promoting fat storage." (PMID 40897667, 2025). "For example, pro‐inflammatory pathways (NF‐κB, JNK) and cytokine signaling (e.g., CRP, IL‐1β) drive IR and β‐cell stress, while PPARγ and leptin signaling mediate obesity‐driven IR." (PMID 40673471, 2025). "Leptin is a hormone, an adipokine produced by fat tissue, with higher concentrations in people with obesity and diabetes." (PMID 40940878, 2025).
Obesity (continued). "Another adipokine, leptin, is a key molecular mediator of the relationship between obesity and BC and is overexpressed in individuals who are obese or overweight." (PMID 40386557, 2025). "When analyzing the entire cohort, we found that circulating leptin levels were higher in patients with severe obesity than in controls, and there was a significant positive correlation between anthropometric measures and leptin." (PMID 40943431, 2025). "Leptin levels are directly proportional to adipose tissue volume and play a key role in the relationship between obesity and hypothyroidism." (PMID 41477173, 2025). "Leptin, an adipokine elevated in obesity due to resistance, promotes podocyte hypertrophy, proliferation, and fibrosis, thereby exacerbating injury." (PMID 41586196, 2025). "Though direct evidence in pandas is limited, X#‘s attenuated EC/CR levels and leptin-estrogen crosstalk disruptions mirror these mechanisms, strengthening obesity’s plausibility as a contributing factor." (PMID 40343364, 2025). "Although circulating leptin levels rise in obesity, bone marrow MSCs often develop leptin resistance, leading to impaired JAK2/STAT3 signaling." (PMID 40852589, 2025). "Mutations in this gene are one of the most common causes of monogenic obesity, and together with the genes encoding leptin and LEPR, MC4R explains 30% of extreme obesity in children." (PMID 41150735, 2025). "Obesity is considered a metabolic disease, in which leptin is used as an indicator of energy in the body." (PMID 40566611, 2025). "Leptin is a functional protein generated through the transcription and translation of the obesity gene, with its receptors widely distributed throughout the body." (PMID 41164182, 2025). "Leptin levels are typically elevated in individuals with obesity, leading to an upregulation of pro-inflammatory cytokines like TNF-a and IL-6." (PMID 40558305, 2025). "In conclusion, gut dysbiosis contributes to obesity through a complex network of endocrine disruptions, involving insulin, leptin, ghrelin, GLP-1, PYY, cortisol, serotonin, and sex hormones." (PMID 41010468, 2025). "Study shows the synergistic effect of sibutramine and leptin in decreased food intake and body weight reduction in diet-induced obesity (DIO) rats." (PMID 41016636, 2025). "Namely, in obesity, adipose tissue deposits release more pro-inflammatory cytokines and adipokines, including leptin and tumor necrosis factor alpha (TNF-α)." (PMID 40722842, 2025). "This study proposes a novel mechanism linking obesity, AT-derived EVs, and leptin to breast cancer progression." (PMID 40485730, 2025). "Elevated serum leptin levels observed in Zn-overloaded rats suggest a disruption in appetite regulation, which contributes to obesity and metabolic syndrome." (PMID 41459237, 2025). "Other biomarkers such as adiponectin, omentin, apelin, leptin, resistin, and fatty‐acid‐binding protein‐4 are also under investigation for their relevance to obesity." (PMID 40551726, 2025). "In leptin-deficient or leptin-resistant HFD models, circulating levels of IL-4 decrease, leading to metabolic abnormalities like obesity, hyperglycemia, IR, liver injury, and changes in AKT, STAT3, and STAT6 pathways." (PMID 41007770, 2025). "The neuroendocrine hormone leptin plays an important role in obesity by regulating food intake, metabolism, and fat distribution." (PMID 40191968, 2025). "Serum leptin and Wnt5a showed significant differences between obesity classes I vs. III (p-values < 0.001 and = 0.002, respectively) and II vs. III (p-values < 0.001 and 0.006, respectively)." (PMID 39837875, 2025). "Leptin showed significant positive correlations with obesity, IR, and creatinine clearance (p < 0.05 all)." (PMID 41162612, 2025). "Adipokines, like leptin, typically increased in obesity, and adiponectin, tendentially reduced in obesity, are crucial players in this intricate interaction." (PMID 40869611, 2025).
Obesity (continued). "The role of obesity in modulating the immune system, particularly through adipocytokines like leptin, has also been proposed as a key factor in the development of asthma in obese children." (PMID 40426941, 2025). "Giving leptin’s characteristics, our goal is to decode a continuous pro-satiety state from plasma leptin concentration collected from a cohort of women with obesity, as an effort to measure the long-term basal satiety in an objective way." (PMID 41036146, 2025). "Consistently, IL36G expression was upregulated by hypoxia, inflammation-related factors (LPS, TNF-α and leptin) and by the adipocyte secretome from patients with obesity in HT-29 cancer cells." (PMID 40268791, 2025). "Biomarkers such as leptin, adiponectin, and certain inflammatory cytokines (e.g., IL‐6 and TNF‐α) have shown promise in predicting the risk of obesity and its associated complications." (PMID 40551726, 2025). "Obesity results in a relative insensitivity to leptin signaling, and leptin insensitivity in POMC and AgRP neurons leads to obesity and diabetes in patients and animal models." (PMID 40501942, 2025). "Leptin reduces appetite, increases energy consumption and reduces weight, while orexin stimulates eating behavior and leads to obesity." (PMID 40551883, 2025). "Meanwhile, leptin production by obesity-altered adipose stem cells has been reported to promote metastasis in TNBC." (PMID 40414892, 2025). "Obesity exacerbates MAFLD and osteoporosis by causing chronic low-grade inflammation in the liver, increasing insulin resistance, affecting leptin and lipocalin secretion, and disrupting intestinal microcirculation." (PMID 40547375, 2025). "In people with obesity, the blood level of leptin is elevated, while the level of ghrelin, which stimulates hunger, is unexpectedly reduced." (PMID 41150735, 2025). "In the context of MetS, the confluence of high leptin levels in obesity and low adiponectin levels in individuals with increased adipose tissue mass is associated with an elevated cardiovascular risk." (PMID 40310144, 2025). "Other endocrine abnormalities in obesity, such as increased leptin, decreased adiponectin, and altered estrogen metabolism, have also been associated with PAH." (PMID 41322909, 2025). "Meanwhile, there is growing interest in developing leptin-based therapeutic strategies aimed at restoring leptin’s efficacy as a treatment for obesity." (PMID 41016636, 2025). "Mice lacking PTP1B in the whole body or in the brain are hypersensitive to leptin and resistant to obesity." (PMID 41251447, 2025). "LEP, a protein containing 167 amino acids produced by adipocytes, has been reported to be related to coronary heart disease, high body mass index, obesity, and heart failure." (PMID 41143005, 2025). "Obesity-associated signals such as CCL2, CSF1, and leptin not only increase macrophages infiltration but also direct their spatial recruitment to metabolically stressed or angiogenic regions of the tumor." (PMID 41310829, 2025). "Obesity and overnutrition elevate leptin levels but lead to leptin resistance, which dulls the regulatory effects of leptin, further contributing to weight gain and insulin resistance." (PMID 40722840, 2025). "While leptin is widely recognized as a molecular link between obesity and breast cancer, the specific role of leptin within EVs remains underexplored." (PMID 40485730, 2025). "Furthermore, a large portion of patients suffered from cardiovascular comorbidities at baseline, including HTN, HLD, and obesity, which have been linked to leptin levels and CAC scores and might have affected the results of our univariate and multivariate analysis." (PMID 39557398, 2025). "The physiological role of leptin appears to be unsuccessful in obesity, leading to high levels of serum leptin (known as leptin resistance), which support the ongoing low-grade inflammation that contributes to chronic illness." (PMID 39940412, 2025).
Obesity (continued). "Subjects with obesity present leptin resistance, affecting energy expenditure and increasing food intake." (PMID 40847538, 2025). "Adipocytokines are immunomodulatory proteins secreted by adipocytes that act in feedback loops linking obesity and cardiometabolic disease, which typically include leptin, adiponectin, interleukin (IL)-6, IL-18, and tumor necrosis factor-alpha (TNF-a)." (PMID 40486661, 2025). "To investigate, we assessed the direct effect of leptin on H3K27 modifiers and CCL2 secretion by ASCs, simulating the leptin‐rich environment of obesity in vitro." (PMID 40518865, 2025). "Leptin, in particular, plays a central role in energy homeostasis by promoting fatty acid oxidation; however, in obesity, hyperleptinemia often reflects leptin resistance, a condition that amplifies insulin resistance." (PMID 41334336, 2025). "This state of exhaustion is likely influenced by immune checkpoint pathways, such as PD-1/PD-L1, and further amplified by leptin, a hormone frequently elevated in obesity." (PMID 40227730, 2025). "Given leptin’s dual role in metabolism and immunity, it is plausible that disruptions in leptin signaling—such as those observed in metabolic syndrome and obesity—contribute to prolonged inflammation and delayed fibrosis resolution in FS." (PMID 40095902, 2025). "The median leptin concentrations of the groups were 41.6 (IQR: 26.8-61.8) ng/mL for those with class II/III obesity and 5.5 (IQR: 4.0-9.1) ng/mL for healthy controls (P < .001)." (PMID 41140715, 2025). "A sub-analysis of adipokine levels according to the different grades of obesity was also performed and only significant differences were found between baseline and 6 m leptin levels in patients with overweight versus grade II obesity." (PMID 40077690, 2025). "In contrast to leptin, adiponectin levels are observed to be reduced in individuals with impaired lung function and obesity." (PMID 40809439, 2025). "The correlation between leptin and TNF-α is known to be associated with inflammatory diseases such as sepsis, psoriasis, preeclampsia, and obesity." (PMID 41153693, 2025). "PI3K signalling is required for leptin effects in the hypothalamus, and a dysfunctional pathway contributes to leptin resistance during diet-induced obesity." (PMID 40216734, 2025). "Obesity in women leads to complex interactions between adipose tissue, insulin, leptin, sex hormones, and other endocrine hormones, which can cause functional abnormalities within the hypothalamic-pituitary-ovarian (HPO) axis." (PMID 41321496, 2025). "Another study, in humans with severe obesity, demonstrated that β‐galactosidase activity is correlated with serum leptin levels, insulin resistance, and increased body fat mass." (PMID 40842420, 2025). "Differences in adipose tissue distribution, the stage of obesity, and methodological variations in leptin measurement can influence such observations." (PMID 41334630, 2025). "In mouse models, obesity accelerates ALL progression by fostering leptin resistance—a condition marked by elevated leptin levels but weakened LEPR signaling." (PMID 40563875, 2025). "So far, several fat mass and obesity-associated (FTO) genes, e.g., MC4R, LEP, LEPR, PCSK1, and POMC, have been identified as instigating childhood obesity." (PMID 40231296, 2025). "Leptin and adiponectin, two major adipokines regulating energy metabolism, are key determinants of metabolic health and disease severity in obesity." (PMID 41367390, 2025). "A possible mechanistic link between altered cerebellar properties and obesity is provided by leptin, a hormone heavily involved in obesity." (PMID 40072905, 2025). "Prior studies in BBS populations highlight the challenges of obesity management, often complicated by hyperleptinemia and leptin resistance." (PMID 41333852, 2025). "Elevated in obesity and metabolic syndrome, leptin promotes endothelial dysfunction through increased oxidative stress, eNOS inhibition, and upregulation of adhesion molecules." (PMID 41155389, 2025).